S100G (S100 calcium binding protein G)
Synonyms: CABP; CABP9K; CALB3; CABP1
Tractability: PROTAC: ubiquitination databases record sites on it.
Gene: Protein-coding gene on chromosome X (16,650,158 to 16,654,670, forward strand). Ensembl gene ENSG00000169906.
Subcellular location (Human Protein Atlas): Cytosol
Gene Ontology:
Molecular function: protein binding; calcium ion binding; calcium-dependent protein binding; transition metal ion binding
Cellular component: cytoplasm; apical plasma membrane; basolateral plasma membrane
Homologues: Orthologues: chimpanzee S100G (100% identical), macaque S100G (99% identical), dog S100G (92% identical), pig S100G (90% identical), rabbit S100G (87% identical), guinea pig S100G (78% identical), rat S100g (78% identical), mouse S100g (75% identical), zebrafish s100a10a (42% identical), zebrafish s100t (34% identical), zebrafish s100s (33% identical), tropical clawed frog s100a11 (28% identical). Paralogues in human: S100A1 (43% identical), S100Z (39% identical), S100B (38% identical), S100A12 (37% identical), S100A4 (37% identical), S100A5 (37% identical), S100P (37% identical), S100A2 (35% identical), S100A11 (34% identical), S100A6 (34% identical), S100A13 (33% identical), S100A10 (32% identical), and 9 more.
Diseases named in the same sentence as S100G in open-access papers:
S100G is named in the same sentence as 25 diseases in open-access papers, as found by Europe PMC text mining. Sharing a sentence is not in itself a finding about the gene and the disease. The quoted sentences say what the papers report.
Hypocalcemia (2 papers, 2024 to 2026). An abnormally decreased calcium concentration in the blood. "Repression of Trpv6 and S100g might contribute to the more severe hypocalcemia and rickets phenotype observed in VdrΔAF2 mice." (PMID 39164247, 2024).
lung carcinoma (2 papers, 2018 to 2024). "Not only are VD and the VDR particularly important in lung cancer management but also vitamin D-dependent proteins, such as calbindins, calretinin, and S100-G, which are crucial in calcium ion binding and may impact lung cancer." (PMID 38928369, 2024). "However, the roles of S100A1, S100A3, S100A7A, S100A12, S10016, and S100G proteins in lung cancer are rarely reported." (PMID 29607329, 2018).
colorectal adenocarcinoma (1 paper, 2020). The most common type of colorectal carcinoma. "The mRNA level of S100G was slightly upregulated in colorectal adenocarcinoma samples (fold change = 1.025) in Skrzypczak's dataset, COAD samples (fold change = 1.19) of Notterman dataset, and READ samples (fold change = 1.025) using Gaedcke's dataset." (PMID 33294444, 2020).
ovarian carcinoma (1 paper, 2018). A malignant neoplasm originating from the surface ovarian epithelium. "Whereas, some other S100 family members, including S100A3, S100A5, S100A7, S100A7A, S100A8, S100A16 and S100G are less reported in ovarian carcinoma." (PMID 30558666, 2018).
pancreatic cancer (1 paper, 2008). "We also noticed increased expression of some X-linked genes related to signal transduction such as Rsk4, Dusp9 and S100g, which have not been reported previously in pancreatic tumors." (PMID 18218118, 2008).
Parkinson disease (1 paper, 2020). A progressive degenerative disorder of the central nervous system characterized by loss of dopamine producing neurons in the substantia nigra and the presence of Lewy bodies in the substantia nigra and locus coeruleus. "S100g (calbindin D28k) is a calcium-binding protein that is best studied for its presence in non-degenerating midbrain dopaminergic neurons in Parkinson’s disease." (PMID 32351369, 2020).
infection (3 papers, 2014 to 2022). The state of being infected such as from the introduction of a foreign agent such as serum, vaccine, antigenic substance or organism. "Furthermore, 72 h after infection, the expression levels of the metallothioneins metallothionein 2A (MT2A) (3.03) and metallothionein 1A (MT1A) (2.58) increased the most, while the lowest FC index was found for the gene encoding the calcium-binding protein S100G (−2.64)." (PMID 35746747, 2022).
tumor (3 papers, 2023 to 2025). "In contrast, domain 13, with high expression of MGP, CPB1, and S100G, points to a region associated with calcification, ECM remodeling, and tumor progression, which may contribute to treatment resistance and poor clinical outcomes." (PMID 41223185, 2025). "As S100A5, S100A7, S100A7A, S100Z, TCHHL1, and S100G are ubiquitously expressed at low levels in both tumor and paratumor samples, they were not included in the following analyses." (PMID 37133437, 2023).
adenocarcinoma (1 paper, 2018). A common cancer characterized by the presence of malignant glandular cells. "S100G (HR = 1.29, 95% CI: 1.03–1.63, and p = 0.0290) and S100Z (HR = 0.91, 95% CI: 0.71–1.16, and p = 0.4300) were not significantly related to prognosis in adenocarcinoma and expression of the other 17 S100 members correlated with worse OS." (PMID 29607329, 2018).
S100G also shares sentences with these, for which no sentence is quoted: cancer (3 papers); diabetes mellitus (2); Type 1 diabetes (2); vitamin D deficiency (2); colitis (1); endometrial carcinoma (1); endometrioid ovarian cancer (1); Hyperglycemia (1); Hypoinsulinemia (1); Insulin resistance (1); medulloblastoma (1); mesothelioma (1); osteosarcoma (1); pituitary cancer (1); rectal tumor (1); rickets (1).